MPO (myeloperoxidase)
Diseases named in the same sentence as MPO in open-access papers (continued):
Sharing a sentence is not in itself a finding about the gene and the disease.
acute pancreatitis (38 papers, 2006 to 2025). An acute inflammatory process that leads to necrosis of the pancreatic parenchyma. "After 24 h, injection of EtOH and POA produced acute pancreatitis indicated by significant increases in histopathological damage and pancreatic myeloperoxidase concentrations." (PMID 33672594, 2021). "In the rats with arginine-induced acute pancreatitis, lycopene treatment reduced tumor necrosis factor-α and myeloperoxidase activity, and down-regulated inducible nitric oxide synthase gene expression in pancreatic tissues." (PMID 33672594, 2021). "MPO has been used as a marker of neutrophil migration in acute pancreatitis studies and has been correlated to the severity of kidney injury." (PMID 26884642, 2016). "In the present study, we showed that netrin-1 protects against acute pancreatitis as shown by reductions in plasma amylase, MPO activity, pancreatic and pulmonary tissue damage, and pro-inflammatory cytokine production." (PMID 23029434, 2012). "Pancreatic MPO activity significantly increased upon development of acute pancreatitis, and peaked at 72 h after the AP model was induced, consistent with the time point at which plasma amylase peaked (P<0.05)." (PMID 23029434, 2012). "Lung MPO activity was also significantly increased upon development of acute pancreatitis, and peaked at 72 h after the AP model was induced." (PMID 23029434, 2012). "In a recent report, it was shown that supramaximal caerulein induced a greater degree of acute pancreatitis in CF mice compared to wild type, based on histological scores, edema, and pancreatic MPO levels." (PMID 16700916, 2006). "Furthermore, Withaferin A reduced myeloperoxidase (MPO) and nitrotyrosine levels and enhanced Nrf2 signaling in acute pancreatitis, highlighting its antioxidant role." (PMID 41394145, 2025). "Besides this, it suppressed MPO activity, improved SOD (superoxide dismutase) activity, and caused apoptosis in mice with acute pancreatitis." (PMID 38230908, 2024). "Curiously, as a result of Galunisertib treatment, a reduced serum levels of MPO, IL-1β and IL-6 were observed in the acute pancreatitis model, implying those factors could also contribute to mesenchymal activation." (PMID 38322992, 2024). "APM also reduced cytokine concentrations and MPO activity in a mouse model of acute pancreatitis." (PMID 37232748, 2023). "Since that acute pancreatitis is an inflammatory disorder of the pancreas, we have also detected that VB 12 reduced the level of MPO in the AP model in vivo and reduced the level of inflammatory factors IL-1β and TNF-α in the supernatant of acinar cell culture in vitro." (PMID 34925701, 2021). "Furthermore, patients with severe acute pancreatitis had elevated levels of cell-free DNA and MPO-DNA conjugates, consistent with NET formation." (PMID 30733719, 2019). "The results of this study suggest that eugenol attenuates the intensity of the histopathological changes and the expression of TNF-α and MPO in the renal parenchyma, while lowering the values of serum urea and creatinine when administered in a rat acute pancreatitis experimental model." (PMID 26884642, 2016). "Besides, the anti-inflammatory effect of dihydro-resveratrol on acute pancreatitis was further evidenced by the declined MPO activity, which is an index of neutrophil sequestration." (PMID 26971398, 2016). "ACS15 significantly attenuated the rise in lung MPO activity in severe acute pancreatitis." (PMID 24278674, 2012). "Pretreatment with EAE (400 mg/kg) reduced significantly the inflammatory response of cerulein-induced acute pancreatitis by ameliorating pancreatic edema, amylase and lipase serum levels, proinflammatory cytokines, myeloperoxidase activity, lipid peroxidation and pathological alteration." (PMID 23008778, 2012).
acute pancreatitis (continued). "Severe, but not mild, acute pancreatitis is associated also with lung injury, which is characterized by sequestration of neutrophils within the lung (i.e., increased lung MPO activity) and histological evidence of lung injury." (PMID 24278674, 2012). "Acute pancreatitis caused a significant decrease in tissue GSH level and Na+, K+-ATPase activity, which was accompanied with significant increases in the pancreatic MDA, luminol and lucigenin chemiluminescences (CL) levels and MPO activity." (PMID 27956946, 2009). "Interestingly, the pretreatment with diazepam (5 mg/kg i.p.)reduced significantly the inflammatory response of acute pancreatitis by ameliorating pancreatic edema, amylase and lipase serum levels, myeloperoxidase activity, pancreatic TNF-alpha, and pathological alteration compared to control group." (PMID 23956866, 2013). "In contrast, the VB12 treatment was unable to reduce the level of serum lipase, the MPO+ neutrophil infiltration and CD11b+ macrophage in pancreatic tissues in mice with CER‐induced acute pancreatitis." (PMID 39415850, 2024). "Furthermore, pancreatic myeloperoxidase (MPO) activity has been thoroughly studied, since it has been shown that it might be used as a marker of neutrophil migration in acute pancreatitis and has been correlated to the severity of pancreatic injury in previously published studies." (PMID 33912302, 2021). "Activities of myeloperoxidase (MPO), a neutrophil marker, increased during acute pancreatitis in pancreas homogenates showing the highest activities at 24 hours." (PMID 31727956, 2019). "Measurements of pancreatic plasma extravasation, pancreatic and lung myeloperoxidase (MPO) activity and serum amylase levels in phospholipase A2(PLA2) – and taurocholate (TAU)-induced acute pancreatitis in rats." (PMID 18510740, 2008). "In contrast, the serum lipase levels and the MPO+ neutrophil infiltration in pancreatic tissues did not change after ATP treatment in the CD320‐ablation mouse models with CER‐induced acute pancreatitis." (PMID 39415850, 2024). "In addition, the results of immunological staining showed that CO-HbV treatment also decreased the MPO accumulation (neutrophil infiltration) and NO2-Tyr accumulation (oxidative product) of acute pancreatitis mice, indicating that CO-HbV attenuated the inflammation and oxidative injury in lungs." (PMID 29847178, 2018).
ischemic stroke (38 papers, 2013 to 2025). A stroke disorder caused by obstruction of blood flow to the brain, due to thrombotic (local blood clot formation) or embolic (due to a blood clot or other material traveling from another site) event. "To further explore the inflammatory pathways involved, we measured MPO activity, an indicator of neutrophil infiltration and inflammation commonly associated with ischemic stroke." (PMID 40076473, 2025). "MPO is an enzyme involved in oxidative stress and inflammation, with elevated levels linked to an increased risk of ischemic stroke due to its role in promoting oxidative damage and vascular inflammation." (PMID 40624693, 2025). "Early studies have identified the increased risk of ischemic stroke with genetic variability of myeloperoxidase." (PMID 37047362, 2023). "The inhibition of signalling pathways, such as TLR2/4-NF-kB, causes a reduction in MPO activity in ischemic stroke models." (PMID 36289828, 2022). "The increase of MPO level in plasma was associated with the severity of ischemic brain damage in ischemic stroke patients." (PMID 32508671, 2020). "Genetic variations in MPO are associated with a higher risk of ischemic stroke." (PMID 37266435, 2023). "MPO genetic variability appears to increase the risk of ischemic stroke and MPO polymorphisms could be associated with the severity of brain damage and functional outcomes." (PMID 32508671, 2020). "Many studies have reported the myeloperoxidase polymorphisms and their consequently increased activity in ischemic stroke patients and that the inflammatory response mediated by myeloperoxidase may be an underlying mechanism of brain injury in ischemic stroke." (PMID 37047362, 2023). "MPO is an enzyme produced by activated neutrophils that plays a critical role in ischemic stroke by driving oxidative stress and inflammation." (PMID 40076473, 2025). "To examine neuroinflammation, we quantified MPO activity—a common indicator of neutrophil infiltration after ischemic stroke." (PMID 41373489, 2025). "In the MR analysis with ischemic stroke as the outcome, we identified 20 positive results, including myeloperoxidase (MPO), CALCRL, and TPGS2." (PMID 40624693, 2025). "Targeting MPO offers a promising therapeutic strategy for ischemic stroke by addressing several key mechanisms of brain injury." (PMID 41373489, 2025). "This study highlights galangin’s ability to suppress MPO activity, which thereby reduces oxidative stress, neuroinflammation, and secondary damage in ischemic stroke." (PMID 40076473, 2025). "In this study, we observed significant upregulation of FKBP5 in ischemic stroke patients, which was associated with increased expression of NET markers, such as H3cit and MPO-DNA complexes." (PMID 41098728, 2025). "Given that Right Middle Cerebral Artery Occlusion (Rt.MCAO) triggers neuroinflammation and subsequent brain injury, we assessed key inflammatory pathways by quantifying MPO activity, a common marker for neutrophil infiltration after ischemic stroke." (PMID 41373489, 2025). "In ischemic stroke, we found that MPO, CALCRL, PPP5C, KTN1-AS1, CCR1, CTB-50L17.9, CCR9, ZNF362, ZIK1, ELP5, CKAP2, NUP88, and SEC16A show risk effects (OR > 1)." (PMID 40624693, 2025). "In this study, we aimed to determine the effects aging has on MPO and how these changes contribute to age-related differences in outcomes after ischemic stroke." (PMID 39325942, 2024). "Using an anti‐MPO antibody, we detected increased infiltration of neutrophils following ischemic stroke." (PMID 38444306, 2024). "In particular, MPO values were highest in ischemic stroke patients with onset at subgroup 2 (6:00–11:59) and lowest in those with onset at subgroup 4 (18:00–23:59)." (PMID 38245621, 2024). "To validate the specificity of MAFA for MPO, we conducted experiments using brains harvested from aged wild-type and MPO-knockout (MPO-KO) mice three days post-ischemic stroke." (PMID 39325942, 2024).
ischemic stroke (continued). "We aimed to determine the effects aging has on MPO and how these changes contribute to age-related differences in outcomes after ischemic stroke." (PMID 39325942, 2024). "The MPO-mediated oxidative stress and inflammation responses become promising therapeutic targets for ischemic stroke." (PMID 38515139, 2024). "Through longitudinal studies between two different age groups, we demonstrated that elevated MPO activity in aging markedly worsened neurological outcomes after ischemic stroke." (PMID 39325942, 2024). "Conversely, the NIHSS scores showed rhythmic change inconsistent with MPO, being highest in ischemic stroke patients with onset at subgroup 1 (00:00–05:59) and lowest in those with onset at subgroup 3 (12:00–17:59)." (PMID 38245621, 2024). "Particularly, NETs, which consists of DNA coated with histones, myeloperoxidase, elastase, and cathepsin G, has been reported participate in the intracranial hemorrhage and ischemic stroke." (PMID 38144176, 2023). "The extent of neutrophil-mediated MPO activity is thus a key determinant of ischemic stroke-related inflammatory activity and brain damage." (PMID 37266435, 2023). "The elevated MPO activity was testified in both patients with ischemic stroke and in experimental animal models." (PMID 36552554, 2022). "Similar findings were demonstrated when confining the propensity matched comparison to the patients with definitive ischemic strokes (N = 105) (p value for significant difference in Anti-Apo A1 IgG was 0.05 and for MPO was < 0.01)." (PMID 35042473, 2022). "Nevertheless, neutrophil-depleted mice had reduced levels of circulating MPO-DNA complexes (112.8% ± 46.6% vs. 231.3% ± 74.8%) and were protected from ischemic stroke brain injury (47.5 ± 15.8 mm3 vs. 73 ± 19.5 mm3)." (PMID 35358095, 2022). "In a study, it was observed that the oral administration of eriodictyol in the doses of 1 mg/kg, 2 mg/kg, and 4 mg/kg has the potential to inhibit the effects of MPO expression and inflammatory cascade in a rat model of permanent ischemic stroke." (PMID 36289828, 2022). "Here, we demonstrate using colocalization of NET-specific markers (H3cit, NE, MPO, and DNA) that NETs are present in brain tissue of ischemic stroke patients." (PMID 35358095, 2022). "The increased MPO in the plasma was found in ischemic stroke patients after receiving t-PA treatment." (PMID 32508671, 2020). "MPO knockout mice had increased cell proliferation and improved neurological outcomes in post-ischemic stroke rats." (PMID 32508671, 2020). "Oral administration of eriodictyol (1, 2, 4 mg/kg) exhibited inhibitory effects on MPO expression and inflammation in a permanent ischemic stroke rat model." (PMID 32508671, 2020). "MPO can be a therapeutic target for attenuating oxidative damage and neuroinflammation in ischemic stroke." (PMID 32508671, 2020). "Hypochlorous acid (HOCl) is a crucial cytotoxic factor contributing to the MPO-mediated oxidative injury in ischemic stroke." (PMID 32508671, 2020). "In patients with ischemic stroke, a reduced amount of intracellular myeloperoxidase (MPO), a key enzyme of neutrophil defense mechanisms, was found." (PMID 32209993, 2020). "A functional MRI study reported the positive correlation between MPO expression and infarct volume in ischemic stroke rat brains." (PMID 32508671, 2020). "Intraperitoneal injection of trigonelline (100 mg/kg), a plant alkaloid from fenugreek seeds, inhibited MPO expression, improved the neurological outcomes and alleviated infarct size in ischemic stroke animal models." (PMID 32508671, 2020). "Inhibition of MPO increases the proliferation and survival of neurons in animal models of ischemic stroke." (PMID 31440125, 2019). "Osthole treatment also attenuates ischemic stroke via inhibition of MPO activity and pro-inflammatory cytokines production in a rat model of middle cerebral artery occlusion." (PMID 23755293, 2013).
ischemic stroke (continued). "After ischemic stroke, due to the destruction of the blood-brain barrier, immune cells such as neutrophils and macrophages infiltrate and microglia are activated in the ischemic areas and release MPO." (PMID 39325942, 2024). "Subsequently, the induction of MPO-HOCl from the exosomes of microglia/macrophage (the Iba-1 positive cells) might contribute to brain damage and neurological deficits in ischemic stroke." (PMID 38515139, 2024). "Our findings suggest that the SIRT1-BMAL1 pathway may be involved in early oxidative stress in ischaemic stroke, which may be related to MPO." (PMID 38245621, 2024). "Importantly, this rise in MPO activity after ischemic stroke in the aged group corresponded to the time of highest mortality in this group (within 48 hours)." (PMID 39325942, 2024). "In ischemic stroke, myeloperoxidase (MPO) activation plays a vital role in brain oxidative damage." (PMID 36552554, 2022). "Furthermore, researchers have also observed elevated MPO activity after ischemic stroke in basic research." (PMID 36439687, 2022). "Moreover, MPO inhibition was reported to reduce neuroinflammation in specimens from patients with Parkinson’s disease and to improve neurogenesis following ischemic stroke in mice." (PMID 36421487, 2022). "Treatment with BoxA significantly reduced plasma MPO-DNA complexes (144.8% ± 56.2% vs. 275.4% ± 52.5%) and improved ischemic stroke outcomes (53.9 ± 26.7 mm3 vs. 88.2 ± 35.2 mm3), confirming a key role for HMGB1 mediating detrimental NET formation in ischemic stroke." (PMID 35358095, 2022). "Thus, MPO inhibitors have translational values as therapeutic candidates for improving the outcomes of ischemic stroke treatment." (PMID 32508671, 2020). "The t-PA treatment increased the MPO level in the plasma of ischemic stroke patients within 1 h." (PMID 32508671, 2020). "Targeting MPO and cellular signaling cascades could be a therapeutic strategy to decrease infarct size and improve the neurological outcomes in ischemic stroke treatment." (PMID 32508671, 2020). "Thus, neutrophil-mediated MPO activation contributes to inflammation and the severity of brain damage during ischemic stroke." (PMID 32508671, 2020). "In addition, the NOTCH4 rs3134931 SNP was highly associated with circulating serum or plasma MPO levels, which were responsible for the incidence as well as development of the CHD and ischemic stroke." (PMID 33317561, 2020). "Natural compound inhibiting MPO for protecting ischemic stroke injury." (PMID 32508671, 2020). "The MPO-mediated nitrosative stress could be a potential player in mediating hemorrhagic transformation in ischemic stroke with the delayed t-PA treatment." (PMID 32508671, 2020). "Myeloperoxidase activation also plays crucial roles in oxidative damage in ischemic stroke." (PMID 32508671, 2020). "Intervention of inhibiting MPO for protecting ischemic stroke injury." (PMID 32508671, 2020). "The ability of acetaminophen to inhibit MPO activity and reduce the production of potent oxidants such as hypobromous acid (HOBr) and hypochlorous acid (HOCl) may partially explain its potential protective effects in ischemic stroke patients." (PMID 40777988, 2025). "Targeting MPO with natural compounds could be a promising strategy for treating ischemic stroke." (PMID 32508671, 2020). "Therefore, MPO can be modulated by multiple cellular signaling mechanisms, and MPO is one of the inflammatory factors contributing to the pathology of ischemic stroke through a complex interaction with different cellular signaling molecules, which remains to be further elucidated." (PMID 32508671, 2020). "Importantly, MPO could be an important molecular target for ischemic stroke treatment practically that allows for a broad intervention time window." (PMID 32508671, 2020). "Herein, we demonstrate the presence of NETs in patients with ischemic stroke, as demonstrated by the upregulation of NET formation markers (H3cit, MPO, and dsDNA)." (PMID 41098728, 2025).